NPLOC4 (NPL4 homolog, ubiquitin recognition factor)
Description:
The ternary complex containing UFD1, VCP and NPLOC4 binds ubiquitinated proteins and is necessary for the export of misfolded proteins from the ER to the cytoplasm, where they are degraded by the proteasome. The NPLOC4-UFD1-VCP complex regulates spindle disassembly at the end of mitosis and is necessary for the formation of a closed nuclear envelope (By similarity). Acts as a negative regulator of type I interferon production via the complex formed with VCP and UFD1, which binds to RIGI and recruits RNF125 to promote ubiquitination and degradation of RIGI.
Synonyms: KIAA1499; NPL4; FLJ20657
Tractability: PROTAC: ubiquitination databases record sites on it; its protein half-life has been measured.
Gene: Protein-coding gene on chromosome 17 (81,556,887 to 81,648,465, reverse strand). Ensembl gene ENSG00000182446.
Subcellular location: Cytoplasm, cytosol; Endoplasmic reticulum; Nucleus
Subcellular location (Human Protein Atlas): Cytosol; Nucleoplasm
Pathways (Reactome):
Metabolism of proteins: Neddylation; Ribosome Quality Control (RQC) complex extracts and degrades nascent peptide
Cellular responses to stimuli: KEAP1-NFE2L2 pathway
DNA Repair: Translesion Synthesis by POLH
Disease: Dengue Virus Genome Translation and Replication
Gene Ontology:
Molecular function: protein binding; ubiquitin binding; ubiquitin protein ligase binding; ATPase binding; K48-linked polyubiquitin modification-dependent protein binding; K63-linked polyubiquitin modification-dependent protein binding; protein-containing complex binding
Biological process: negative regulation of RIG-I signaling pathway; negative regulation of type I interferon production; retrograde protein transport, ER to cytosol; ubiquitin-dependent protein catabolic process; ERAD pathway; Golgi organization; proteasome-mediated ubiquitin-dependent protein catabolic process; rescue of stalled ribosome; ribosome-associated ubiquitin-dependent protein catabolic process
Cellular component: nucleoplasm; nucleus; UFD1-NPL4 complex; VCP-NPL4-UFD1 AAA ATPase complex; ATPase complex; cytosol; endoplasmic reticulum; nuclear outer membrane-endoplasmic reticulum membrane network; RQC complex
Genetic constraint (gnomAD): Loss-of-function variants: 15 observed, 54.24 expected, observed/expected ratio (o/e) 0.28, 90% interval 0.18 to 0.43. The upper end of that interval is the gene's LOEUF score, 0.43, which puts it in group 1 of 6, group 1 being the genes least tolerant of losing a copy. Missense variants: 450 observed, 632.83 expected, observed/expected ratio (o/e) 0.71, 90% interval 0.66 to 0.77. Synonymous variants: 280 observed, 252.77 expected, observed/expected ratio (o/e) 1.11, 90% interval 1 to 1.22.
Homologues: Orthologues: chimpanzee NPLOC4 (99% identical), mouse Nploc4 (97% identical), dog NPLOC4 (97% identical), guinea pig NPLOC4 (97% identical), rat Nploc4 (97% identical), macaque NPLOC4 (97% identical), rabbit NPLOC4 (87% identical), tropical clawed frog nploc4 (85% identical), pig NPLOC4 (84% identical), zebrafish nploc4 (83% identical), Drosophila melanogaster Npl4 (49% identical), Caenorhabditis elegans npl-4.1 (38% identical), and 1 more.
Diseases named in the same sentence as NPLOC4 in open-access papers:
NPLOC4 is named in the same sentence as 47 diseases in open-access papers, as found by Europe PMC text mining. Sharing a sentence is not in itself a finding about the gene and the disease. The quoted sentences say what the papers report.
bladder cancer (5 papers, 2019 to 2025). "NPLOC4, also known as NPL4, is uncharacterized in HCC but has been revealed as an important oncogene in bladder cancer and a critical target of the anticancer drug disulfiram." (PMID 35300417, 2022).
myopia (4 papers, 2019 to 2025). "Other suggestive signals were located near loci previously associated with retinal features, myopia, or abnormality of refraction, such as the TSPAN10/NPLOC4/PDE6G locus or the retinoid acid receptor beta RARB, associated with retinal vasculature in a previous GWAS." (PMID 38365752, 2024).
Strabismus (4 papers, 2019 to 2023). A misalignment of the eyes so that the visual axes deviate from bifoveal fixation. "NPLOC4 encodes the homolog, ubiquitin recognition factor and has been previously associated with macular thickness and the risk of strabismus and corneal and refractive astigmatism." (PMID 34127677, 2021). "Additionally the NPLOC4-TSPAN10 locus is associated with strabismus, the abnormal alignment of the eyes." (PMID 36848389, 2023). "A second GWAS, using self-reported strabismus in the UK Biobank, identified a locus on chromosome 17q25, which extends across the NPLOC4-TSPAN10-PDE6G gene cluster." (PMID 32780866, 2020). "Given the association of variants at the NPLOC4–TSPAN10–PDE6G locus and AMD, we carried out a sensitivity analysis examining the association between strabismus and rs75078292 after excluding UK Biobank participants with self-reported AMD." (PMID 31073882, 2019).
clear cell renal cell carcinoma (2 papers, 2020 to 2023). "Pan-cancer analysis indicated that NPLOC4 was highly expressed in most types of cancer, including clear cell renal cell carcinoma, bladder urothelial carcinoma, and papillary renal cell carcinoma." (PMID 37993584, 2023).
gastric cancer (2 papers, 2022 to 2023). A primary or metastatic malignant neoplasm involving the stomach. "In our previous research, DSF + Cu was found to inhibit ubiquitin-mediated proteolysis by acting on NPLOC4, resulting in gastric cancer cell apoptosis." (PMID 37993584, 2023).
lung carcinoma (2 papers, 2023 to 2025). "Recently, a seven-gene m6A/m5C risk model, comprising METTL3, NPLOC4, RBM15, YTHDF1, IGF2BP1, NSUN3, and NSUN7, was developed to stratify the prognosis of early-stage lung cancer." (PMID 40279954, 2025). "NPLOC4 may be an independent prognostic factor for lung cancer." (PMID 37993584, 2023).
sarcoma (2 papers, 2022). A usually aggressive malignant neoplasm of the soft tissue or bone. "Furthermore, we measured Nploc4 and p97 in gastrocnemius of another model of cancer cachexia we routinely use, mice carrying MCG101 (methylcholanthrene‐induced sarcoma)." (PMID 35611892, 2022).
age-related macular degeneration (1 paper, 2023). Age-related loss of vision in the central portion of the retina (macula), secondary to retinal degeneration. "NPLOC4 is known as a muscle degeneration-related gene because it has two SNPs (rs6565597 and rs9894429) that are related to age-related macular degeneration." (PMID 37653517, 2023).
Astigmatism (1 paper, 2018). A type of refraction error associated with abnormal curvatures on the anterior and/or posterior surface of the cornea. "Three of these loci also demonstrated genome-wide significant association with refractive astigmatism: LINC00340, HERC2/OCA2 and NPLOC4/TSPAN10." (PMID 30306274, 2018).
Atrophy (1 paper, 2022). Any weakening or degeneration, especially through lack of use. "Altogether, DSF reduced Nploc4 from the soluble fraction of muscles and spared body weight and muscles from C26‐induced atrophy in mice." (PMID 35611892, 2022). "Because p97 is increased in denervation‐induced and fasting‐induced muscle atrophy, it would be interesting to measure the gene expression of Nploc4 in these two models of muscle atrophy to see whether Nploc4 can be added to the list of atrogenes." (PMID 35611892, 2022).
Cachexia (1 paper, 2022). Severe weight loss, wasting of muscle, loss of appetite, and general debility related to a chronic disease. "Instead, the increase in Nploc4 in muscles during cachexia and ALS might be explained by increased ERAD, in addition to enhanced proteolysis of sarcomeric proteins." (PMID 35611892, 2022). "Notably, there was no Nploc4 induction in TA from non‐cachectic female mice bearing 4T1, supporting Nploc4 induction as a hallmark of muscle wasting during cachexia and not in cancer in general." (PMID 35611892, 2022).
Corneal astigmatism (1 paper, 2018). "Single marker-based association tests for corneal astigmatism identified four genome-wide significant loci (P < 5 × 10−8) near the genes ZC3H11B (1q41), LINC00340 (6p22.3), HERC2/OCA2 (15q13.1) and NPLOC4/TSPAN10 (17q25.3)." (PMID 30306274, 2018).
lung adenocarcinoma (1 paper, 2023). A carcinoma that arises from the lung and is characterized by the presence of malignant glandular epithelial cells. "In lung adenocarcinoma, we considered that the presence of some gene hot-spot mutations affected the survival of patients with the expression of NPLOC4." (PMID 37993584, 2023). "We analyzed the effect of the expression of NPLOC4 in lung adenocarcinoma on the survival of patients, and found that there was no significant different survival between high and low groups." (PMID 37993584, 2023).
lung squamous cell carcinoma (1 paper, 2023). "Shorter survival periods and tumor growth were linked to high NPLOC4 expression.Disulfiram (DSF) combined with copper (Cu) targets NPLOC4 to achieve antitumor effects in lung squamous cell carcinoma." (PMID 37993584, 2023). "Using bioinformatics, this study evaluated NPLOC4 as a prognostic marker for patients with lung squamous cell carcinoma." (PMID 37993584, 2023).
lymph node metastasis (1 paper, 2023). "We found that patients with TNM stages III–IV, as well as patients with lymph node metastasis, had higher NPLOC4 expression." (PMID 37993584, 2023). "We found that NPLOC4 expression is associated with shorter OS, later AJCC staging, lymph node metastasis, and poor prognosis in LUSC." (PMID 37993584, 2023).
pancreatic adenocarcinoma (1 paper, 2023). "However, during the study, our research group found that in pancreatic adenocarcinoma, the group with high NPLOC4 expression had longer survival times, suggesting that the effect of NPLOC4 is specific to the tumor type." (PMID 37993584, 2023).
retinal degeneration (1 paper, 2025). Degeneration of the retina. "Depletion of seven genes (Eif2s1, Hspa5, Hspa8, Nploc4, Hyou1, Ufd1, and Vcp) showed an exacerbating effect on the Rho-Pro23His retinal degeneration compared to the Cas9+/− mice." (PMID 41282224, 2025).
cancer (28 papers, 2018 to 2025). A tumor composed of atypical neoplastic, often pleomorphic cells that invade other tissues. "Through genetic and pharmacological approaches using in vitro and in vivo mouse models, we show that Nploc4 seems the most important interacting protein of p97 with a role in muscle atrophy associated to cancer or ALS." (PMID 35611892, 2022). "Cases 3 and 4 exhibited low NPLOC4 expression in cancer tissues." (PMID 37993584, 2023). "Cases 1 and 2 exhibited high NPLOC4 expression in cancer tissues." (PMID 37993584, 2023). "Our data clearly show that among the p97 cofactors, Nploc4 is the one most induced in atrophying muscles from three unrelated models of cancer cachexia (C26, LLC, and RXF393) and from SOD1G93A mice, even though this induction did not anticipate muscle depletion." (PMID 35611892, 2022). "In the TA of LLC‐bearing mice, a model of cancer cachexia but in C57BL/6 background, the mRNA levels of p47, Ufd2, Nploc4, and Herpud1 were all induced by about 50%, while Ufd1, Derl1, Rnf31, and Hsp90 did not change." (PMID 35611892, 2022).
tumor (23 papers, 2018 to 2026). "uncovered genes, including TLE4 and IKZF2, that are associated with T-cell exhaustion and effector function via screening of CAR-T cells, and identified genes, including RELA and NPLOC4, that are essential for tumor susceptibility to tumor killing via the reciprocal screening of GSCs." (PMID 35874698, 2022). "Evaluation of NPLOC4 expression in conjunction with clinicopathological data from 83 patients revealed higher NPLOC4 expression in tumor tissues, both in the analysis of cancerous and paraneoplastic tissues and in the paired analysis of cancerous and paraneoplastic tissues." (PMID 37993584, 2023). "To learn whether Nploc4 was also induced in muscle in a tumour‐free model of muscle atrophy, as ALS, by qPCR, we analysed the expression of selected p97 cofactors in TA muscles from 14‐week‐old or 17‐week‐old SOD1G93A mice." (PMID 35611892, 2022). "Finally, in LUSC, DSF combined with Cu might induce tumor cell apoptosis by inhibiting NPLOC4, which increases ubiquitinated protein accumulation." (PMID 37993584, 2023). "Furthermore, we found that NPLOC4 expression is higher in tumor cells than in normal cells." (PMID 37993584, 2023).
NPLOC4 also shares sentences with these, for which no sentence is quoted: alcohol abuse (3 papers); infection (2); viral infections (2); Alcohol (1); alcohol addiction (1); amyotrophic lateral sclerosis (1); bladder urothelial carcinoma (1); breast carcinoma (1); Cardiovascular disease (1); colon cancer (1); colorectal cancer (1); frontotemporal dementia (1); glioma (1); hepatocellular carcinoma (1); Huntington disease (1); immune diseases (1); liver cancer (1); medulloblastoma (1); melanoma (1); muscle degeneration (1); neurodegenerative disease (1); osteosarcoma (1); Ovarian Tumor (1); Paget's disease of the bone (1); papillary renal cell carcinoma (1); serous ovarian carcinomas (1); triple-negative breast carcinoma (1); type 2 diabetes (1).